POLD1 (DNA polymerase delta 1, catalytic subunit)
Diseases named in the same sentence as POLD1 in open-access papers (continued):
Sharing a sentence is not in itself a finding about the gene and the disease.
lung carcinoma (7 papers, 2016 to 2022). "First, the frequency of POLD1 mutations in Chinese lung cancer patients was higher than that recorded in COSMIC35." (PMID 31673068, 2019). "It was found that the frequency of POLE variants was not statistically different from that in COSMIC database, while the frequency of POLD1 variants was significantly higher in lung cancer." (PMID 31673068, 2019). "Therefore, the cause of the frequency difference of POLD1 variants in Chinese lung cancer patients and its significance for immunotherapy deserve further investigation." (PMID 31673068, 2019). "POLQ, BRCA2, ATM, ATR, PARP4, and POLD1 alterations were most commonly observed in the entire advanced lung cancer cohort." (PMID 34604048, 2021).
ovarian carcinoma (6 papers, 2021 to 2025). A malignant neoplasm originating from the surface ovarian epithelium. "Besides endometrial carcinoma, cervical and ovarian cancers were also assessed for the importance of POLD1 mutations and expression changes." (PMID 36980791, 2023). "The small group of patients who were diagnosed with both breast and ovarian cancer had germline P/LP variants in BRCA1 (25%), BRCA2 (50%), and POLD1 (25%)." (PMID 40710012, 2025). "Five female POLE ED variant heterozygotes developed ovarian cancer (OC) between the ages of 33 and 45, including one with bilateral disease age 40 years, but no OCs were found in POLD1 ED variant heterozygotes (Fisher’s exact test, p = 0.31))." (PMID 33948826, 2022).
endometrial tumors (5 papers, 2015 to 2023). "In contrast, our data show that patients with DHODH overexpression and wild-type copies of POLE and POLD1 are significantly associated with low-grade (G1 and G2) endometrial tumors (** p < 0.01, **** p < 0.0001)." (PMID 38136273, 2023). "Her endometrial tumor exhibited characteristics that were in keeping with a POLD1 pathogenic phenotype, including high infiltrating lymphocytes, a high tumor mutation burden, and the presence of the SBS10d mutational signature." (PMID 38067377, 2023). "In our index patient, we evaluated her endometrial tumor’s whole-exome genome for a POLD1 DNA proofreading deficiency mutational signature." (PMID 38067377, 2023). "While the genomic analysis from the patient’s endometrial tumor suggests the pathogenic role of the POLD1 p.D402N mutation, it is unclear if the observed increased tumor mutation burden and SBS10d mutational signature are directly caused by the patient’s germline p.D402N." (PMID 38067377, 2023). "Clinical-grade whole-exome sequencing (WES) of the endometrial tumor revealed high TMB (141 mut/Mb), microsatellite stable status, and loss of heterozygosity for the POLD1 allele." (PMID 38067377, 2023). "Interestingly, 72% and 73% of endometrial tumors with DHODH overexpression co-occurrence with a POLE and POLD1 mutation are significantly associated with high-grade tumor stages, respectively (** p < 0.01, **** p < 0.0001)." (PMID 38136273, 2023). "In addition, endometrial tumors with DHODH overexpression also show an increase in mutated POLE and POLD1 genes (* p < 0.5)." (PMID 38136273, 2023). "Furthermore, our study may provide a foundation to accurately classify grade III endometrial tumors based on DHODH overexpression associated with the POLE and POLD1 mutation, which may contribute to the better selection of patients for future therapeutic strategies." (PMID 38136273, 2023).
glioblastoma (5 papers, 2018 to 2024). The most malignant astrocytic tumor (WHO grade IV). "When considering only the six POLE/POLD1 variant carriers with a glioblastoma CNS WHO grade 4, their mean age was 59 years and their mean overall survival was 21 months." (PMID 37990341, 2023). "Similarly, the mean overall survival of 21 months observed here in POLE/POLD1 germline variant carriers with a glioblastoma compares favorably with the median overall survival of 8 months for glioblastomas according to a recent CBTRUS Statistical Report." (PMID 37990341, 2023). "Similarly, around 25% of glioblastoma patients with rare POLE/POLD1 germline variants compiled here were affected by giant cell glioblastoma, although this tumor type typically accounts for < 1% of all glioblastomas." (PMID 37990341, 2023). "Taken together, the viability of LN-229 glioblastoma and MMR-deficient HCT116 cells carrying CRISPR/Cas9-mediated POLE or POLD1 variants was markedly reduced." (PMID 37990341, 2023). "Additionally, germline variants in POLD1, located at 19q13.33, were detected in 2/34 (6%) patients with 1p/19q-codeleted oligodendrogliomas, while POLE variants were identified in 2/4 (50%) glioblastoma patients with a spinal metastasis." (PMID 37990341, 2023). "Furthermore, non-benign POLE and POLD1 variants were identified in tumor DNA of 5.3% (POLE) or 2.5% (POLD1) glioblastomas." (PMID 37990341, 2023). "In LN-229 glioblastoma cells, genotyping of the CRISPR/Cas9-edited cells revealed 1/48 (2%) cell clones harboring a mutant POLE allele, 1/48 (2%) cell clones devoid of WT POLE alleles, 20/85 (24%) cell clones harboring a mutant POLD1 allele, and 0/85 cell clones devoid of WT POLD1 alleles." (PMID 37990341, 2023). "Multicolor FISH analysis of LN-229 glioblastoma cells revealed a hyperdiploid karyotype with more than two copies of the long arms of chromosome 12 harboring the POLE gene at 12q24.33 and possibly of chromosome 19 harboring the POLD1 gene at 19q13.33." (PMID 37990341, 2023). "Therefore, to exclude a germline origin for the POLE variants detected in the glioblastoma, the Case 1 patient’s PBL genomic DNA was sequenced but no POLE or POLD1 variants were detected." (PMID 38789506, 2024). "In contrast, the fact that no viable POLD1 knockout LN-229 glioblastoma cell clone could be generated here suggests that there is no sufficient compensation by DNA polymerase ε in this cellular model." (PMID 37990341, 2023).
oligodendroglioma (5 papers, 2020 to 2023). A well-differentiated (WHO grade II), diffusely infiltrating neuroglial tumor, typically located in the cerebral hemispheres. "Taken together, rare deleterious POLD1 germline variants were detected in two of 34 (6%) oligodendroglioma patients." (PMID 37990341, 2023). "The development of oligodendroglioma may be particularly favored by POLD1 germline variants, as oligodendrogliomas are characterized by a 1p/19q codeletion affecting the POLD1 locus at 19q13.33." (PMID 37990341, 2023). "And indeed, we detected rare POLD1 germline variants in two of 34 (6%) oligodendroglioma patients." (PMID 37990341, 2023). "Therefore, we performed POLD1 mutational analysis on leukocyte DNA of 33 other oligodendroglioma patients." (PMID 37990341, 2023). "We identified the rare homozygous POLD1:c.2546G>A p.(R849H) missense variant predicted to be deleterious affecting amino acids located within the multifunctional domain of POLD1 in one sporadic oligodendroglioma patient." (PMID 37990341, 2023). "We observe that different genes belonging to this pathway exhibit different trends, for example genes such as POLD1(chr19), RPA2(chr1), and LIG1(chr19) loose a copy in IDH-mut oligodendrogliomas, while genes RPA3(chr19), PMS2(chr19), PCNA(chr20) and POLD2(chr7) gain a copy in IDH-wt GBM." (PMID 36918656, 2023).
pancreatic cancer (5 papers, 2014 to 2025). "Mutations in POLD1 and POLE genes encoding the catalytic subunit of Polδ and Polε, respectively, have been found in several types of cancer such as colorectal, endometrial, gastric and pancreatic cancer." (PMID 32656256, 2020).
prostate carcinoma (5 papers, 2017 to 2024). A carcinoma that arises from epithelial cells of the prostate gland. "Despite some recent reports that POLE and POLD1 variants predispose to prostate cancer, only one patient developed prostate cancer (aged 51) in the families analysed." (PMID 33948826, 2022). "In a study involving a cohort of 4129 prostate cancer patients 1.8% (74/4129) of patients had POLE/POLD1 mutations." (PMID 34063238, 2021). "The discovery of POLD1 as a novel biomarker related to prostate cancer metastasis offers a promising avenue for enhancing treatment of prostate cancer metastasis." (PMID 38918844, 2024). "This study provides evidence supporting the significant role of POLD1 in prostate cancer." (PMID 38918844, 2024). "Based on this rationale, a phase 2 study of toripalimab (a PD-1 antibody) in patients with advanced solid organ tumors including prostate cancer and POLE/POLD1 positive status has been initiated." (PMID 34063238, 2021).
colorectal tumours (4 papers, 2014 to 2022). "Microsatellite instability (MSI) and POLD1 mutations are usually described in colorectal tumours in patients with polyposis syndrome but rarely found in breast tumours." (PMID 32104204, 2020). "Cancer driver mutations found in crypts from normal intestine, and colorectal neoplasms from individuals with POLE/POLD1 germline mutations, showed SBS and ID mutational spectra similar to genome-wide spectra from normal intestinal crypts from these individuals." (PMID 34594041, 2021). "Twenty-three of the 27 POLD1 heterozygotes had a colorectal tumour phenotype." (PMID 33948826, 2022).
deafness (4 papers, 2021 to 2025). An inherited or acquired condition characterized by the complete loss of the ability to hear from one or both ears. "The knowledge of the link between POLD1 defects and the development of highly diverse clinical symptoms ranging from depletion of subcutaneous fat to deafness and bone abnormalities strongly represents a key challenge." (PMID 33618333, 2021).
Fanconi anemia (4 papers, 2020 to 2022). Fanconi anemia (FA) is a hereditary DNA repair disorder characterized by progressive pancytopenia with bone marrow failure, variable congenital malformations and predisposition to develop hematological or solid tumors. "Fanconi anemia (FA) is a rare recessive disease characterized by DNA damage repair deficiency, and DNA polymerase δ (whose catalytic subunit is encoded by POLD1, also known as CDC2) is closely related to DNA damage repair." (PMID 32432416, 2020).
hereditary colorectal cancer (4 papers, 2014 to 2025). "Finally, related to hereditary colorectal cancer, 11 variants in POLE and 6 variants in POLD1 were found." (PMID 36232851, 2022).
lymphoma (4 papers, 2013 to 2025). A malignant (clonal) proliferation of B- lymphocytes or T- lymphocytes which involves the lymph nodes, bone marrow and/or extranodal sites. "Analyzing the database DepMap, we noted a significant correlation (Pearson r = 0,781; Spearman ρ = 0,671; p = 0.000004) between the expression of HDAC10 and POLD1 in 32 human lymphoblastic leukemia and lymphoma cell lines." (PMID 40301616, 2025). "The segregation analysis revealed that the POLD1 variant c.1941delG, p.(Lys648fs*46) segregated in six additional members of the family beside the index case: four siblings (three fulfilling SPS 2010’s criteria and one diagnosed with lymphoma at age of 46) and her two healthy daughters." (PMID 36756361, 2023).
mismatch repair deficiency (4 papers, 2022 to 2025). "Some mutational processes can lead to high TMB, such as POLE/POLD1 mutation, mismatch repair deficiency, UV light, tobacco smoking, AID/APOBEC activation." (PMID 35935970, 2022). "In addition to the biallelic germline mutations in an MMR gene causing mismatch repair deficiency, these childhood tumors arising in the setting of CMMRD often acquire mutations in the proofreading domain of DNA polymerase epsilon (POLE) or delta (POLD1)." (PMID 38079020, 2023).
progeroid syndrome (4 papers, 2018 to 2025). A group of rare genetic disorders which mimic physiological aging, making affected individuals appear to be older than they are. "Case 34, which showed two cell populations with distinct mitotic recombination sites and apparent segUPD on the long arm of chromosome 19, contained the POLD1 gene in the segUPD region, which is a candidate gene for the progeria-like phenotype." (PMID 34284807, 2021). "The initial full‐length sequencing of common genes implicated in progeroid syndromes, such as LaminA/C, ZMPSTE24, POLD1, and BNF1, revealed homozygous base pair mutations in exon 9 of LaminA/C c.1579C>T (p.R527C) in three patients (here referred to as MAD1, MAD2, MAD3)." (PMID 39661729, 2025). "Lessel et al21 tested 50 patients with a putative diagnosis of nonclassical WS (ie, progeroid syndrome without WRN, LMNA, BANF1, and ZMPSTE24 mutations) and found causative POLD1 mutations in 8 patients." (PMID 30023403, 2018).
Werner syndrome (4 papers, 2018 to 2023). "For example, the impairment of POLD1 activity has been identified in developmental disorders such as MDPL and Werner syndrome which are both characterized by signs of premature aging affecting more than one tissue or organ." (PMID 37551728, 2023). "The defective POLD1 function can induce cellular senescence and aging‐related pathologies, including the reduced lifespan of mice and the occurrence of mandibular hypoplasia, deafness, progeroid features, and lipodystrophy (MDPL), Werner syndrome, multiple tumors, and Alzheimer's disease (AD)." (PMID 37551728, 2023).
Alzheimer disease (3 papers, 2022 to 2023). A progressive, neurodegenerative disease characterized by loss of function and death of nerve cells in several areas of the brain leading to loss of cognitive function such as memory and language. "POLD1 can also be employed for the prognosis of invasive breast carcinoma and AD (Alzheimer's disease) and can even be a therapeutic target for their treatment." (PMID 35620275, 2022).
breast tumor (3 papers, 2020 to 2024). "In addition, POLD1 mutations were found to predispose to endometrial and breast tumors." (PMID 39684352, 2024). "Sequencing data from a breast tumor harboring a somatic frameshift variant in the same residue as the germline POLD1 c.3305delC (p.Pro1102Leufs*22) showed neither hypermutation nor the POLE/D1-associated mutational signature." (PMID 32792570, 2020).
cervical cancer (3 papers, 2018 to 2022). A primary or metastatic malignant neoplasm involving the cervix. "Of TLS genes, increased expression of SPRTN, DTL, POLD1, PCNA, and VCP occurred most often in cervical cancers." (PMID 36266721, 2022).
cutaneous melanoma (3 papers, 2018 to 2022). A primary melanoma arising from atypical melanocytes in the skin. "In the cutaneous melanoma PanCancer Atlas study (provisional), 11 of 27 samples (40.7%) with CTCFL mutations had lesions in one of the four MSI associated genes or the POLE or POLD1 genes." (PMID 30275357, 2018).
hereditary mixed polyposis syndrome (3 papers, 2016 to 2022). "Recently, genome-wide screening efforts led to the identification of mutations affecting the expression of GREM1 as the cause of hereditary mixed polyposis syndrome (HMPS) and mutations in the POLD1 and POLE genes as the cause of polymerase proofreading-associated polyposis (PPAP) syndrome." (PMID 27279102, 2016).
liver cancer (3 papers, 2013 to 2025). An epithelial or non-epithelial malignant neoplasm that arises from the liver. "The research showed that primary liver cancer associated with POLD1 gene." (PMID 24137319, 2013). "OU detected POLD1 gene expression by RT-PCR, and found out that the expression in liver cancer tissue was significantly higher than tissue adjacent to carcinoma." (PMID 24137319, 2013).
mesothelioma (3 papers, 2012 to 2020). A usually malignant and aggressive neoplasm of the mesothelium which is often associated with exposure to asbestos. "It was proposed that POLD1 was directly or indirectly related to platinum resistance in mesothelioma." (PMID 32762026, 2020).
metastatic colorectal cancer (3 papers, 2023 to 2025). "POLD1 is a protein critical for proofreading and fidelity in DNA replication, and POLD1 mutations are positive predictors for the survival benefit from immune checkpoint blockers, as well as exceptional chemotherapy response in a metastatic colorectal cancer patient." (PMID 36719559, 2023).
stomach carcinoma (3 papers, 2017 to 2020). "A CRC and a lymphoid neoplasm harboring POLD1 p.Arg352Cys, as well as a stomach carcinoma with POLD1 p.Arg525Trp, displayed hypermutation but not the POLE/D1 ED-associated signatures." (PMID 32792570, 2020).
acute lymphoblastic leukemia (2 papers, 2023 to 2025). Leukemia with an acute onset, characterized by the presence of lymphoblasts in the bone marrow and the peripheral blood. "Intriguingly, in acute lymphoblastic leukemia (ALL), POLD1 upregulation may promote the relapse of this disease." (PMID 36980791, 2023).
CMMRD syndrome (2 papers, 2022). "Taken together, the clinical and genetic findings in the entire family, the exclusion of CMMRD syndrome by absence of MSI in blood leukocytes, and the tumor mutational phenotype render overwhelming evidence of a digenic CPS due to the PMS2 and POLD1 (L)PVs in the siblings." (PMID 36291559, 2022).
esophagitis (2 papers, 2022 to 2024). An acute or chronic inflammatory disease affecting the esophageal wall. "MTHFR (rs1801133), NQO1 (rs1800566), ZNF217 and POLD1 were risk alleles related to a higher susceptibility to pneumonitis and esophagitis." (PMID 38255239, 2024). "Moreover, through their roles in genome integrity and replicative fidelity, somatic alterations in ZNF217 and POLD1 might also serve as risk predictors of high-grade pneumonitis and esophagitis." (PMID 35912186, 2022).
gastric adenocarcinoma (2 papers, 2022 to 2025). "In stomach adenocarcinoma (STAD), POLD1-mutant tumors exhibit significantly higher PD-L1 mRNA expression compared to wild-type tumors (P=0.0072), indicative of adaptive immune resistance." (PMID 40661943, 2025).
hereditary cancer syndrome (2 papers, 2023). "Germline variations in the DNA polymerase genes, POLE and POLD1, can lead to a hereditary cancer syndrome that is characterized by frequent gastrointestinal polyposis and multiple primary malignant tumors." (PMID 37746257, 2023).
Hutchinson-Gilford progeria syndrome (2 papers, 2020 to 2021). "Of the 71 patients with AWS, a subset was shown to carry mutations in LMNA, a gene known to be mutated in the Hutchinson-Gilford Progeria syndrome (HGPS), or in POLD1, a DNA polymerase involved in several DNA repair pathways." (PMID 33194896, 2020).
invasive breast carcinoma (2 papers, 2020 to 2022). A carcinoma that infiltrates the breast parenchyma. "High expression of POLD1 may serve as a potential prognostic indicator for invasive breast cancer." (PMID 33519918, 2020).
leukemia (2 papers, 2023 to 2025). A malignant (clonal) hematologic disorder, involving hematopoietic stem cells and characterized by the presence of primitive or atypical myeloid or lymphoid cells in the bone marrow and the blood. "To scrutinize the interplay between HDAC10 and POLD1 expression, we assessed their levels by immunoblot in various leukemia cell types that were incubated with PZ48." (PMID 40301616, 2025). "For example, PRMT5 regulation of POLD1 and ATM via AS have been previously suggested by us and others in leukemias and uveal melanomas." (PMID 37861290, 2023).
lung adenocarcinoma (2 papers, 2021 to 2022). A carcinoma that arises from the lung and is characterized by the presence of malignant glandular epithelial cells. "In addition, the high expression levels of H2AFX, MCM2, MCM7, and POLD1 correlate with poor prognosis of lung adenocarcinoma (LUAD)." (PMID 33442399, 2021).